ACTB (actin beta)
Diseases named in the same sentence as ACTB in open-access papers (continued):
Sharing a sentence is not in itself a finding about the gene and the disease.
Cirrhosis (2 papers, 2009 to 2023). A chronic disorder of the liver in which liver tissue becomes scarred and is partially replaced by regenerative nodules and fibrotic tissue resulting in loss of liver function. "Although the correlation between ACTB level and cirrhosis has not been evidenced, a recent study has shown that ACTB is involved in circulatory inflammation and angiogenesis." (PMID 36725885, 2023). "Our further investigation into the association between these DEGs and immune infiltration also revealed the correlations between ACTB, TAGLN, VIM, SOX9 and immune cells, supporting that these genes play a vital role in cirrhosis via regulating immune infiltration." (PMID 36725885, 2023).
deafness (2 papers, 2018 to 2020). An inherited or acquired condition characterized by the complete loss of the ability to hear from one or both ears. "Although the underlying cause of deafness in ACTB patients is unclear, animal studies have demonstrated a critical role of beta-actin in the maintenance of hair cell stereocilia function, with progressive hearing loss starting at 6 weeks of age in ACTB knockout mice." (PMID 29788902, 2018).
dengue fever (2 papers, 2018 to 2024). "based on our study, we suggest ACTB with HPRT/GAPDH combination for normalization in qPCR for precise quantification of transcripts in dengue infected studies." (PMID 30071880, 2018). "It has been reported that ACTB protein can increase the replication efficiency of HIV and can be a potential biomarker in dengue virus infection." (PMID 38707036, 2024). "In the present study best endogenous gene among COX, ACTB, GAPDH, HMBS, HPRT and B2M during dengue fever." (PMID 30071880, 2018). "Similarly, ACTB has also been widely used in dengue related studies while GAPDH has been used in dengue studies as sole reference gene or with combination of other reference genes." (PMID 30071880, 2018).
developmental disabilities (2 papers, 2018 to 2024). "Patients carrying mutations in ACTB or ACTG1 predominately suffer from developmental disabilities, which can be directly linked to cortical malformations of varying severity." (PMID 38446501, 2024).
dilated cardiomyopathy (2 papers, 2020 to 2024). Cardiomyopathy which is characterized by dilation and contractile dysfunction of the left and right ventricles. "The remaining pathways were all detected with a predominance of control proteins, such as the Citrate cycle (TCA cycle) (P-value < 0.0001; ACLY, DLST, PDHA1, PDHB), except Dilater cardiomyopathy (DCM) (P-value = 0.0006; ACTB, ADCY8, LOC396781, TPM1)." (PMID 38409238, 2024).
endometrial cancer (2 papers, 2024 to 2025). Primary or metastatic malignant neoplasm involving the endometrium (mucous membrane that lines the endometrial cavity). "Six of them were upregulated in endometrial cancer patients (CLU, SERPINC1, ITIH4, C1RL, APOC3 and DSC1), while ten were downregulated (APCS, C9, APOA1, ALB, APOA4, CFHR1, ITIH2, and ACTB)." (PMID 39194522, 2024). "However, recent research has indicated that GAPDH, along with ACTB and 18S rRNA, may not exhibit stable expression in endometrial cancer." (PMID 41008854, 2025).
endometriosis (2 papers, 2020 to 2024). The growth of functional endometrial tissue in anatomic sites outside the uterine body. "Repeated genes associated with P-phase (ACTB, ANXA4, BPIFB1, EPHX1, MUC5B, PRDX2, and VIM) could indicate stronger genetic causes associated with pathophysiology of endometriosis." (PMID 32474803, 2020). "Moreover, cyto-hub gene analysis revealed that CSNK2A1, CSNK2A2, TOP1, PRKACA, RBM39 (plasma), ALB, ACTB, GAPDH, FN1, APOA1 (serum), S100-A9, CXCL1, IL1RN, CSTA, S100-A8 (menstrual blood) and THBS1, ALB, CD44, ANXA2, and LUM (urine) were the top 5 proteins expressed in women with endometriosis." (PMID 39061077, 2024).
glaucoma (2 papers, 2022). Increased pressure in the eyeball due to obstruction of the outflow of aqueous humor. "The finding of MSLN in the tear might be stressed, however, if one considers the increased level of extracellular matrix compounds as a pattern for CRVO and glaucoma; the presence of MSLN seems reasonable due to its importance in cell adhesion as well as PPR4 and ACTB." (PMID 36498980, 2022).
Huntington disease (2 papers, 2021 to 2023). Huntington disease (HD) is a rare neurodegenerative disorder of the central nervous system characterized by unwanted choreatic movements, behavioral and psychiatric disturbances and dementia. "Finally, based on pathway, three genes were associated with cytoskeletal regulation by Rho GTPase pathway (ACTB, PFN1 and CFL1) while two genes were associated each with glycolysis (GAPDH and PGK1) and Huntington disease (GAPDH and ACTB)." (PMID 34681026, 2021).
hypercoagulability (2 papers, 2022 to 2025). "ACTB (β-actin), normally intracellular, can appear extracellularly during neutrophil extracellular trap formation, cell injury, or release of extracellular vesicles and exosomes, and is associated with endothelial damage and hypercoagulability." (PMID 40821834, 2025).
Hypertension (2 papers, 2022 to 2025). The presence of chronic increased pressure in the systemic arterial system. "Lastly, to the best of our knowledge none of the previous EWAS or TWAS published on hypertension related phenotypes have reported KMT2A, ATM, and ACTB among their top findings." (PMID 39972178, 2025).
idiopathic scoliosis (2 papers, 2013 to 2019). A scoliosis with no known cause. "The classification accuracy for Idiopathic Scoliosis in the anamnesis with expression measurement of ACTB and GAPDH with use of ANN based on 6-18-16-1 architecture was 8 of 9 (88%)." (PMID 23289769, 2013). "The classification accuracy for positive Idiopathic Scoliosis anamnesis only with the expression measurements of ACTB and GAPDH with the use of ANN based on 6-18-16-1 architecture was 8 of 9 (88%)." (PMID 23289769, 2013). "Specially designed artificial neural network model proved possible association between expression level of ACTB, GAPDH and positive familial history of Idiopathic Scoliosis." (PMID 23289769, 2013). "In addition, possible association between expression level of ACTB, GAPDH and familial history of idiopathic scoliosis was proved." (PMID 31653238, 2019). "An artificial neural network (ANN) was developed that could serve to differentiate between familial and sporadic cases of idiopathic scoliosis based on the expression levels of ACTB and GAPDH in different tissues of scoliotic patients." (PMID 23289769, 2013). "The analysis indicates the relationship between level of expression of ACTB, GAPDH and familial Idiopathic Scoliosis." (PMID 23289769, 2013). "The aim of the study was to investigate whether the expression levels of ACTB and GAPDH in different tissues of idiopathic scoliosis patients could be used as a source of data for specially developed artificial neural network in order to predict the positive family history of index patient." (PMID 23289769, 2013). "The aim of the study was to investigate whether the expression levels of ACTB and GAPDH in different tissues of idiopathic scoliosis patients could be used as source of data for specially developed artificial neural network in order to predict the positive family history of index patients." (PMID 23289769, 2013).
Immunodeficiency (2 papers, 2021 to 2025). Failure of the immune system to protect the body adequately from infection, due to the absence or insufficiency of some component process or substance. "In addition, a point mutation in the β-actin gene (ACTB) itself has been reported in a single patient presenting with immunodeficiency, thrombocytopenia, but also intellectual and developmental impairments." (PMID 34249918, 2021). "Whole-exome sequencing identified a heterozygous ACTB p.Gln360ProfsTer4 variant in a patient with BRWS1 and combined immunodeficiency." (PMID 40748410, 2025).
invasive breast carcinoma (2 papers, 2021 to 2023). A carcinoma that infiltrates the breast parenchyma. "For example, featured genes such as COL1A1, COL5A1, FN1, and ACTB are involved in invasive breast carcinoma and osteogenesis imperfecta, a heritable bone fragility disorder associated with short stature and abnormalities." (PMID 34858485, 2021).
liver fibrosis (2 papers, 2023 to 2025). "ECM remodeling is essential in liver fibrosis, and the upregulation of actin cytoskeleton-associated genes (COCH and ACTB) denotes increased ECM deposition and cellular motility, which are characteristics of liver fibrosis and HCC progression." (PMID 40901642, 2025). "Therefore, we hypothesized that ACTB gene may be involved in the immune response related to liver fibrosis." (PMID 36725885, 2023).
mammary adenocarcinoma (2 papers, 2023 to 2025). "Some mouse mutation lines in ACTB showed the phenotype “increased mammary adenocarcinoma incidence” and “abnormal smooth muscle morphology”." (PMID 36674696, 2023). "Cell-type specificity was also found on the ACTB expression level in mammary adenocarcinoma cells." (PMID 40149991, 2025).
mastitis (2 papers, 2009 to 2021). Inflammation of breast tissue during lactation or postpartum due to an obstructed duct or infection.
meningioma (2 papers, 2011 to 2016). A generally slow growing tumor attached to the dura mater. "Those genes plus GAPDH and ACTB were compared in an increased number of meningiomas and control tissues." (PMID 21806841, 2011). "Eight highest ranked reference genes (CASC3, EIF2B1, IPO8, MRPL19, PGK1, POP4, PPIA, and RPL37A) plus GAPDH and ACTB were then analyzed in 35 meningiomas, arachnoidea, dura mater and normal brain." (PMID 21806841, 2011). "Bestkeeper-1 considered ACTB unsuitable as reference gene in meningiomas and their control tissues." (PMID 21806841, 2011). "However GAPDH and ACTB as the most used reference genes in meningioma qPCR experiments were further analyzed." (PMID 21806841, 2011). "Additionally results from the current study indicate that widely used GAPDH and ACTB are both inappropriate reference genes for meningiomas." (PMID 21806841, 2011). "Additionally the most used reference genes in meningioma qPCR experiments ACTB and GAPDH were also chosen although being only ranked in fifteenth respectively eighteens place and being considered inconsistent with a standard deviation (SD) higher than 1 by Bestkeeper-1." (PMID 21806841, 2011). "Bestkeeper-1 considered ACTB inconsistent with SD = 1.00 in meningiomas and their control tissue, whereas PGK1 was inconsistent in meningiomas (SD = 1.04)." (PMID 21806841, 2011). "So far various reference genes (GAPDH, ACTB, S18, TBP) were used in qPCR experiments in meningiomas, although GAPDH was mainly used for normalizations." (PMID 21806841, 2011). "Established housekeeping genes in meningioma RT-qPCR experiments are genes such as glyceraldehyde-3-phosphate dehydrogenase (GAPDH) and β-Actin (ACTB) as well as ribosomal RNA (18S rRNA) and TATA binding box protein (TBP)." (PMID 21806841, 2011).
multiple myeloma (2 papers, 2020 to 2024). "This or the causality of the observed mutations in DLBCL and multiple myeloma need further investigation by future screening studies of additional patients and functional studies of ACTB or ACTG1 mutants in appropriate models or patient material." (PMID 32349449, 2020). "For only a few of the congenital mutations functional and/or biochemical consequences have been studied and, interestingly, some of these map close to the positions of the mutations in ACTB or ACTG1 in DLBCL or multiple myeloma." (PMID 32349449, 2020). "In contrast, most of the mutations in ACTB and ACTG1 in DLCBL and multiple myeloma are concentrated in the N-terminal half of the sequence." (PMID 32349449, 2020). "Using the crystal structure of the ACTB monomer, we mapped the amino acid alterations in ACTB and ACTG1 resulting from missense mutations observed in the DLBCL and multiple myeloma patient samples." (PMID 32349449, 2020). "ACTB mutations are found primarily in DLBCL and ACTG1 mutations are most frequent in multiple myeloma." (PMID 32349449, 2020). "Together, this suggests that ACTB and ACTG1 mutations are potentially more than passenger mutations in DLBCL and multiple myeloma, respectively." (PMID 32349449, 2020). "In between DLBCL and multiple myeloma, there are no common mutational sites found in ACTB or ACTG1." (PMID 32349449, 2020).
osteoporosis (2 papers, 2023 to 2025). A condition of reduced bone mass, with decreased cortical thickness and a decrease in the number and size of the trabeculae of cancellous bone (but normal chemical composition), resulting in increased fracture incidence. "Abnormalities in ACTB expression or function can impair osteoclast activity, leading to imbalances in bone resorption and formation, which is a hallmark of osteoporosis." (PMID 40919176, 2025). "In a study on postmenopausal osteoporosis subjects, it was shown that ACTB was aberrated by being an unsuitable house-keeping gene for expression assays." (PMID 37239981, 2023).
ovarian tumor (2 papers, 2013 to 2014). "In conclusion, for an accurate gene expression assay in ovarian tumor tissues, homogeneous tissues as starting materials and normalization based on multiple validated reference genes, such as PPIA, RPLP0, ACTB, and TBP, are recommended." (PMID 24776823, 2014).
sarcoma (2 papers, 2016 to 2025). A usually aggressive malignant neoplasm of the soft tissue or bone. "The detection of ACTB::FOSB fusion is consistent with PMH’s diagnosis and supports its differentiation from other sarcomas, with both diagnostic and potential therapeutic implications." (PMID 40277775, 2025). "We analyzed the expression of the stemness genes c-Myc, KLF4, Nanog, and OCT3/4 that were previously normalized to ACTB, with the identified top-ranking HKG for CSC and native cells, in sarcoma and carcinoma, respectively (GAPDH and YWHAZ for sarcoma, and PPIA and HMBS for carcinoma)." (PMID 26894994, 2016).
thyroid cancer (2 papers, 2020 to 2025). "We used LASSO Cox regression to construct a model for the evaluation of thyroid cancer prognosis, and a risk model consisting of six genes (ACSL5, HSD17B11, CCL5, NCF2, PSME1, and ACTB) was subsequently developed." (PMID 40299520, 2025). "Further validation using qRT–PCR in 100 paired thyroid cancer and adjacent normal tissues revealed consistent upregulation of ACSL5 and NCF2 in tumour tissues and downregulation of HSD17B11, CCL5, and ACTB." (PMID 40299520, 2025). "Next, the expression levels of CTNNB1, ACTB, and CCND1 in thyroid carcinoma were also determined." (PMID 33363164, 2020). "Only three miRNA–gene pairs (miR-876-3p-CTNNB1, miR-876-3p-ACTB, and miR-876-3p-CCND1) revealed a statistically negative expression relationship in thyroid carcinoma." (PMID 33363164, 2020).
viral myocarditis (2 papers, 2022 to 2024). Myocarditis that is caused by an infection with a viral agent. "The gene ACTB, encoding one of six different actin proteins, which are involved in structure, integrity, cell motility, and intercellular signaling, was enriched in the viral myocarditis pathway." (PMID 36398072, 2022). "In order to clarify the molecular network regulating the hypertrophy of goose pectoral muscles, researchers observed the distributions of ACTB in the previously enriched KEGG pathways, and found that ACTB seemed to regulate muscle hypertrophy mainly through the viral myocarditis pathway." (PMID 39504833, 2024). "Moreover, in order to reveal the molecular network of ACTB regulating the hypertrophy of goose pectoral muscles, the viral myocarditis was identified as a pivotal pathway because it reflects the direct link between ACTB and DMD who can encode dystrophin protein." (PMID 39504833, 2024). "CXCL12, C3, FN1, COL1A2, ACTB, VCAM1, and MMP2 were identified and finally verified as the hub genes, mainly enriched in pathways like leukocyte transendothelial migration, PI3K-Akt signaling pathway, viral myocarditis, rheumatoid arthritis, and platelet activation." (PMID 36398072, 2022).
acute pancreatitis (1 paper, 2016). An acute inflammatory process that leads to necrosis of the pancreatic parenchyma. "In studies of caerulein-induced murine acute pancreatitis, ACTB, GAPDH, 18sRNA, beta-2 microglobulin (B2M), and hypoxanthine phosphoribosyltransferase 1 (HPRT1) have been frequently used as reference genes for comparison of mRNA transcription in pancreatic tissue." (PMID 27069927, 2016). "The expression levels of ACTB, TUBB, and B2M were found to be significantly upregulated during acute pancreatitis, whereas the expression level of 18sRNA was downregulated." (PMID 27069927, 2016). "Similar to ACTB, TUBB was not an appropriate reference gene because its expression fluctuated with the pathophysiological process of acute pancreatitis." (PMID 27069927, 2016).
alcoholic liver diseases (1 paper, 2014). A disorder caused by damage to the liver parenchyma due to alcohol consumption. "We chose 18S rRNA for our endogenous control, as it displays the least amount of variance in all stages of alcoholic liver disease in humans (compared to GAPDH, ACTB, and SFRS4)." (PMID 25542004, 2014).
astrocytomas (1 paper, 2015). "Sema3C mRNA values determined in 74 gliomas (9 grade I astrocytomas, 28 grade II astrocytomas, 13 grade III astrocytomas, and 24 grade IV astrocytomas) were normalized to mRNA levels of the β-actin-encoding gene ACTB, which has been used as an internal control." (PMID 26032848, 2015).
B-cell lymphomas (1 paper, 2023). "Mutational profiling using a custom panel of 168 genes associated with aggressive B-cell lymphomas confirmed mutations in ACTB, ARID1B, DUSP2, DTX1, HLA-B, PTEN, and TNFRSF14." (PMID 36975733, 2023).
bladder tumor (1 paper, 2023). "The expression level was very high for both genes in blood tissues compared to the bladder tumor tissues after normalization with the housekeeping gene ACTB." (PMID 37876438, 2023).
bladder urothelial carcinoma (1 paper, 2024). "Single-cell analysis revealed that ACTB, DSTN, and MYL6 were highly expressed in different bladder urothelial carcinoma subtypes, but MYH10 showed a low expression." (PMID 38584831, 2024).
brain injury (1 paper, 2025). Acute and chronic (see also brain INJURIES, CHRONIC) injuries to the brain, including the cerebral hemispheres, CEREBELLUM, and brain STEM. "However, increased ACTB expression has been reported in the injured brain tissue of traumatic brain injury mouse models." (PMID 40672462, 2025).
cholesteatoma (1 paper, 2020). A pathologic process characterized by the proliferation of keratinizing squamous epithelium resulting in the accumulation of keratin and cells in the middle ear and/or mastoid. "For TC samples from healthy controls and cholesteatoma patients, all three programs ranked ACTB and GAPDH among the most stable genes." (PMID 32915926, 2020). "Validation of reference genes using c-MYC expression confirmed the suitability of ACTB and GAPDH as reference genes and showed an upregulation of c-MYC in middle ear mucosa during cholesteatoma." (PMID 32915926, 2020).
chronic kidney disease (1 paper, 2023). Impairment of the renal function secondary to chronic kidney damage persisting for three or more months. "The Rap1 signaling pathway and platelet activation pathway were found to be important in the development of chronic kidney disease (CKD), as were DMPs TLN1 and ACTB, as well as one malonylated site." (PMID 37833721, 2023).